ZDHHC7 (zDHHC palmitoyltransferase 7)
Description:
Golgi-localized palmitoyltransferase that catalyzes the addition of palmitate onto various protein substrates and therefore functions in several unrelated biological processes. Has no stringent fatty acid selectivity and in addition to palmitate can also transfer onto target proteins myristate from tetradecanoyl-CoA and stearate from octadecanoyl-CoA (By similarity). Palmitoylates sex steroid hormone receptors, including ESR1, PGR and AR, thereby regulating their targeting to the plasma membrane and their function in rapid intracellular signaling upon binding of sex hormones. Palmitoylates GNAQ, a heterotrimeric G protein, regulating its dynamic localization at the plasma membrane and is thereby involved in GNAQ-dependent G protein-coupled receptor signaling pathways. Also functions in ligand-induced cell death by regulating the FAS signaling pathway through the palmitoylation and stabilization of the receptor at the plasma membrane. In epithelial cells, palmitoylates SCRIB and regulates its localization to the plasma membrane, regulating indirectly cell polarity and differentiation. Also palmitoylates JAM3 and promotes its expression at tight junctions and regulates its function in cell migration. Palmitoylates the glucose transporter GLUT4/SLC2A4 and controls the insulin-dependent translocation of GLUT4 to the plasma membrane (By similarity). In brain, could also palmitoylate SNAP25 and DLG4/PSD95 (By similarity). Could also palmitoylate DNAJC5 and regulate its localization to the Golgi membrane (By similarity). Could also palmitoylate NCDN (By similarity). May play a role in follicle stimulation hormone (FSH) activation of testicular Sertoli cells (By similarity). Activates pyroptosis by catalyzing palmitoylation of gasdermin-D (GSDMD) (By similarity).
Synonyms: FLJ10792; ZNF370; FLJ20279; SERZ-B; SERZ1; DHHC7
Tractability: Antibody: UniProt predicts a signal peptide or a membrane-spanning region. PROTAC: ubiquitination databases record sites on it.
Target class: Enzyme; Transferase
Gene: Protein-coding gene on chromosome 16 (84,974,175 to 85,011,536, reverse strand). Ensembl gene ENSG00000153786.
Subcellular location: Golgi apparatus membrane
Subcellular location (Human Protein Atlas): Golgi apparatus
Pathways (Reactome):
Signal Transduction: Extra-nuclear estrogen signaling
Gene Ontology:
Molecular function: palmitoyltransferase activity; protein-cysteine S-palmitoyltransferase activity; protein-cysteine S-myristoyltransferase activity; protein-cysteine S-stearoyltransferase activity
Biological process: androgen receptor signaling pathway; negative regulation of catabolic process; peptidyl-L-cysteine S-palmitoylation; polarized epithelial cell differentiation; positive regulation of D-glucose transmembrane transport; progesterone receptor signaling pathway; protein localization to plasma membrane; protein palmitoylation; regulation of Fas signaling pathway; regulation of G protein-coupled receptor signaling pathway; regulation of protein localization to cell-cell junction; regulation of protein localization to plasma membrane; steroid hormone receptor signaling pathway; glucose import in response to insulin stimulus; protein targeting to membrane
Cellular component: Golgi apparatus; Golgi membrane; endoplasmic reticulum
Genetic constraint (gnomAD): Loss-of-function variants: 12 observed, 36.79 expected, observed/expected ratio (o/e) 0.33, 90% interval 0.21 to 0.53. The upper end of that interval is the gene's LOEUF score, 0.53, which puts it in group 2 of 6, group 1 being the genes least tolerant of losing a copy. Missense variants: 378 observed, 415.19 expected, observed/expected ratio (o/e) 0.91, 90% interval 0.84 to 0.99. Synonymous variants: 179 observed, 158.01 expected, observed/expected ratio (o/e) 1.13, 90% interval 1 to 1.28.
Homologues: Orthologues: chimpanzee ZDHHC7 (100% identical), macaque ZDHHC7 (100% identical), rat Zdhhc7 (95% identical), guinea pig ZDHHC7 (95% identical), mouse Zdhhc7 (95% identical), dog ZDHHC7 (94% identical), pig ZDHHC7 (92% identical), tropical clawed frog zdhhc7 (84% identical), zebrafish zdhhc7 (77% identical), Caenorhabditis elegans dhhc-7 (31% identical), Drosophila melanogaster Dnz1 (29% identical), Caenorhabditis elegans dhhc-4 (21% identical), and 6 more. Paralogues in human: ZDHHC3 (60% identical), ZDHHC6 (26% identical), ZDHHC21 (25% identical), ZDHHC20 (24% identical), ZDHHC1 (23% identical), ZDHHC12 (23% identical), ZDHHC2 (22% identical), ZDHHC15 (21% identical), ZDHHC9 (20% identical), ZDHHC14 (20% identical), ZDHHC18 (20% identical), ZDHHC19 (19% identical), and 5 more.
Diseases named in the same sentence as ZDHHC7 in open-access papers:
ZDHHC7 is named in the same sentence as 40 diseases in open-access papers, as found by Europe PMC text mining. Sharing a sentence is not in itself a finding about the gene and the disease. The quoted sentences say what the papers report.
hepatocellular carcinoma (4 papers, 2023 to 2026). A malignant tumor that arises from hepatocytes. "In hepatocellular carcinoma (HCC), ZDHHC7 overexpression correlates with poor outcomes." (PMID 40977744, 2025).
inflammatory bowel disease (4 papers, 2021 to 2025). A spectrum of small and large bowel inflammatory diseases of unknown etiology. "For example, disruption of signal transducer and activator of transcription 3 (Stat3) S-palmitoylation cycling by genetic deletion of Zdhhc7 or pharmacological inhibition of APT-2 ameliorates inflammatory gene expression and colitis in an animal model of inflammatory bowel disease." (PMID 37926281, 2023). "Since increased STAT3 activation and Th17 cell population are markers of inflammatory bowel disease (IBD), the expression of Zdhhc7 and STAT3 target genes were studied in patients with IBD." (PMID 36467682, 2022).
autoimmune disease (3 papers, 2024 to 2025). A disorder resulting from loss of function or tissue destruction of an organ or multiple organs, arising from humoral or cellular immune responses of the individual to their own tissue constituents. "Also, our results indicate ZDHHC7 as a potential therapeutic target for MAVS-related autoimmune diseases." (PMID 39141356, 2024). "Since we revealed that ZDHHC7 increases MAVS oligomerization and enhances type I interferon production, inhibition of ZDHHC7 might be a therapeutic strategy alleviating these autoimmune diseases." (PMID 39141356, 2024). "Therefore, small-molecule inhibitors of palmitoyl-acyltransferase ZDHHC7 or directly targeting NLRP3 Cys126 residue can potentially suppress inflammasome activation and thus may be useful for treating inflammation and autoimmune diseases." (PMID 38583156, 2024).
breast carcinoma (3 papers, 2016 to 2025). "We also observed across studies highly elevated expression of ZDHHC7 in kidney cancer cell lines and PPT1 in breast cancer cell lines, opening potential avenues for research into the role of these enzymes in these cancers." (PMID 36760531, 2023). "ZDHHC7 was elevated in kidney cancer cell lines in both datasets, and PPT1 was highly expressed in cell lines from breast cancer tumors." (PMID 36760531, 2023).
colitis (3 papers, 2022 to 2025). Inflammation of the colon. "Animal experiments show that the knockdown of Zdhhc7 or inhibition of APT2 to interrupt the palmitoylation-depalmitoylation cycle alleviates the symptoms of colitis in a mouse model, suggesting that the STAT3 palmitoylation cycle and its regulatory enzymes may be new therapeutic targets for colitis." (PMID 40959086, 2025).
Anxiety (2 papers, 2021 to 2025). Intense feelings of nervousness, tension, or panic often arise in response to interpersonal stresses. "Previously detected increased locomotion of Zdhhc7 KO females was assumed as behavioural disinhibition and increased exploration because of the simultaneously observed reduced anxiety." (PMID 39856044, 2025). "In addition, ZDHHC7 also palmitoylates gamma-aminobutyric acid (GABAA) receptors, which are major mediators of fast synaptic inhibition in the mammalian brain and are involved in anxiety and object recognition memory." (PMID 33880616, 2021).
cardiac hypertrophy (2 papers, 2023 to 2025). "The key role of gene-based regulatory mechanisms: “ZDHHC3 and ZDHHC7, localized in the Golgi apparatus, have been identified as key regulatory factors in cardiac hypertrophy because they participate in the palmitoylation process of RAC1." (PMID 40969373, 2025). "Further investigation identified Rac1 as a target of zDHHC3 in the heart, and both Zdhhc3 and Zdhhc7 were shown to be important in the initiation of cardiac hypertrophy with pressure overload stimulation." (PMID 37926281, 2023). "Genetic deletion of Zdhhc3 in combination with Zdhhc7 reduces cardiac hypertrophy during the early response to pressure overload stimulation but not over longer time periods." (PMID 37926281, 2023). "Here we performed a gain-of-function screen in the mouse and identified the Golgi-localized enzymes zDHHC3 and zDHHC7 as regulators of cardiac hypertrophy." (PMID 37926281, 2023). "Moreover, cardiac hypertrophy in response to 2 weeks of chronic angiotensin-II infusion was not significantly altered by deletion of Zdhhc3 or Zdhhc7 alone or in combination." (PMID 37926281, 2023).
ovarian carcinoma (2 papers, 2020 to 2021). A malignant neoplasm originating from the surface ovarian epithelium. "Of note, ZDHHC7, not previously identified to play a role in ovarian cancer, encodes a zinc finger protein that regulates a tumor suppressor important for establishing and maintaining epithelial cell polarity." (PMID 34215221, 2021).
Bartter syndrome (1 paper, 2021). "Importantly, Zdhhc7-/- mice developed symptoms characteristic of human Bartter syndrome (BS) type IV because ZDHHC7 protein may affect ClC-K-barttin channel activation." (PMID 34576064, 2021).
cardiomyopathy (1 paper, 2023). A disease of the heart muscle or myocardium proper. "Here, we surveyed zDHHC S-acyltransferase enzymes and observed that activity of zDHHC3 and zDHHC7 at the cytoplasmic surface of the Golgi promotes hypertrophic signaling and cardiomyopathy in vivo." (PMID 37926281, 2023). "The most homologous S-acyltransferase to zDHHC3 is another Golgi-localized enzyme, zDHHC7, and AAV9-mediated overexpression of this enzyme in the heart similarly induced cardiomyopathy within 3 weeks." (PMID 37926281, 2023).
heart failure (1 paper, 2023). Inability of the heart to pump blood at an adequate rate to meet tissue metabolic requirements. "Here, we performed an in vivo screen using recombinant adeno-associated virus (AAV)-mediated overexpression, which identified the closely related Golgi-localized enzymes zDHHC3 and zDHHC7 as inducers of cardiac maladaptation, decompensation, and heart failure." (PMID 37926281, 2023).
mental disorder (1 paper, 2021). A disease that has its basis in the disruption of mental process. "In addition, ZDHHC7 palmitoylates sex steroid hormone receptors and is, therefore, indirectly linked to mental disorders that often occur because of or in conjunction with stress." (PMID 33880616, 2021).
ovarian clear cell cancer (1 paper, 2025). An invasive malignant neoplasm that arises from the ovary and is characterized by a predominance of clear and hobnail malignant epithelial cells. "It has been reported that ZDHHC7 may regulate the nuclear localization of YAP1 in ovarian clear cell carcinoma, and the inhibition of ZDHHC7 enhances ferroptosis by activating YAP1, although it is uncertain whether YAP1 is palmitoylated." (PMID 40814339, 2025).
peritonitis (1 paper, 2024). Inflammation of the peritoneum (tissue that lines the abdominal wall and covers most of the organs in the abdomen). "Additionally, Zdhhc7 KO mice were more resistant to MSU-induced peritonitis, with lower neutrophil and macrophage infiltration in peritoneal lavage fluid and diminished IL-1β levels in the serum of Zdhhc7 KO mice." (PMID 38583156, 2024).
uterine cancer (1 paper, 2025). Primary or metastatic malignant neoplasm involving the uterine corpus and/or the cervix.
virus infection (1 paper, 2024). "Whether and how palmitoylation of MAVS by ZDHHC7 directly regulates mitochondrial metabolism and function upon virus infection awaits further investigation." (PMID 39141356, 2024).
tumor (7 papers, 2021 to 2025). "Kaplan–Meier survival analysis showed that high ZDHHC7 expression was significantly associated with improved prognosis in OS patients, suggesting a potential tumor-suppressive role for ZDHHC7 in OS development." (PMID 40416361, 2025). "Our findings demonstrated that ZDHHC7 was highly associated with tumor-infiltrating immune cells." (PMID 36286021, 2022). "The results revealed that ZDHHC7 expression was significantly correlated with tumor purity in 11 cancer types." (PMID 36286021, 2022). "For example, ZDHHC7‐mediated palmitoylation of the polarity protein Scribble (SCRIB) is essential for its membrane localisation and tumour‐suppressive function; loss of this modification mislocalises SCRIB, leading to Hippo pathway inhibition and YAP activation." (PMID 40903842, 2025). "ZDHHC7-mediated SCRIB palmitoylation enhances tumor suppressive activity of SCRIB76." (PMID 37828054, 2023). "Several studies have revealed that Scribble without ZDHHC7-mediated palmitoylation is mislocalized, resulting in disruption of cell polarity and loss of its tumor suppressor activity in oncogenic pathways." (PMID 36286021, 2022). "Therefore, the lower ZDHHC7 expression in stage III vs stage II samples is consistent with reduced tumor suppressor activity." (PMID 34215221, 2021). "We demonstrated that SPRY4 undergoes a dynamic palmitoylation cycle regulated by ZDHHC7 and PPT1, which modulates MAPK signaling and subsequently affects tumor cell proliferation, migration, apoptosis, and drug resistance." (PMID 40416361, 2025). "We found that ZDHHC7 was most relevant to malignancy of HCC among palmitoyltransferases according to expression level, prognosis and tumor stage." (PMID 38051779, 2023). "The results showed that genes correlated with ZDHHC7 were significantly enriched in the MYC targets V1/V2, G2M checkpoint, mitotic spindle and E2F targets, which are involved in cancer cell proliferation, tumor growth, and tumor metastasis." (PMID 36286021, 2022). "Furthermore, we found that the expression of ZDHHC7 is associated with infiltration levels of some types of immune cells in the tumor microenvironment (TME), and we explored the relationship between ZDHHC7 expression and immune checkpoint (ICP) genes across 33 cancer types." (PMID 36286021, 2022).
cancer (6 papers, 2021 to 2023). A tumor composed of atypical neoplastic, often pleomorphic cells that invade other tissues. "We first investigated the mutation frequency of ZDHHC7/20/21 across various cancers via the cBioPortal database." (PMID 36286021, 2022). "In the previous analysis, we revealed the dynamic expression of ZDHHC7 in human organ development and cancer." (PMID 36286021, 2022). "Next, we found that BRCA, LIHC, LUSC, and PRAD were the four cancer types most greatly correlated with ZDHHC7 expression at the level of immune infiltration." (PMID 36286021, 2022). "In comparison with organ development, the expression of ZDHHC7/20/21 showed opposite expression patterns in eight cancer types." (PMID 36286021, 2022). "Totally, these results suggest that ZDHHC7 had close associations with the TME and provided novel insights into the treatment of cancers." (PMID 36286021, 2022). "The results showed that CD4 memory resting T cells, macrophages M2, and follicular helper T cells were the three immune cell subtypes most highly correlated with ZDHHC7 expression across multiple cancers." (PMID 36286021, 2022). "We found that the expression levels of most palmitoylation regulators altered significantly after birth, with ZDHHC7/20/21 showing opposite expression patterns in cancers." (PMID 36286021, 2022). "For instance, palmitoyl-acyltransferase ZDHHC7 showed a negative association with DNA damage and hormone AR pathways in seven and eight cancer types, respectively." (PMID 37978524, 2023). "Moreover, we further explored the relationships between the expression of ZDHHC7/20/21 and the prognosis of cancer patients in multiple cancers using the GEPIA website." (PMID 36286021, 2022). "In particular, ZDHHC7/20/21 exhibited converse expression patterns in multiple cancer types." (PMID 36286021, 2022). "In addition, in many other cancer types such as LAML, LUSC, and UVM, high ZDHHC7 expression meant worse prognosis, which implies that ZDHHC7 was a potential cancer biomarker." (PMID 36286021, 2022). "Our previous analysis suggests that ZDHHC7 may be a potential prognostic pan-cancer biomarker, so we evaluated the relationship between ZDHHC7 expression and TMB, MSI and neoantigens." (PMID 36286021, 2022). "Therefore, we explored the correlation between ZDHHC7 expression and levels of immune cell infiltration across cancer types using the TIMER database." (PMID 36286021, 2022). "Finally, we evaluated the potential biological pathways affected by ZDHHC7 across human organ development and cancers." (PMID 36286021, 2022). "In addition, we systematically explored the association of ZDHHC7 expression levels with the TME and found that ZDHHC7 might be a potential prognostic and immunological pan-cancer biomarker." (PMID 36286021, 2022). "Finally, GSEA analysis revealed that ZDHHC7 might impact cancer progression by MYC targets V1/V2, G2M checkpoint, mitotic spindle and E2F targets pathway." (PMID 36286021, 2022). "Our study found that ZDHHC7 negatively correlated with the immune, stromal and ESTIMATE scores of the TME in many cancer types." (PMID 36286021, 2022). "Here, we calculated the Pearson correlation coefficient between ZDHHC7 expression and TMB, MSI and neoantigens across multiple cancers." (PMID 36286021, 2022). "Moreover, we examined the function of ZDHHC7, ZDHHC20 and ZDHHC21 in human organ development and cancer using PubMed in NCBI." (PMID 36286021, 2022). "ZDHHC7 and ZDHHC21 are conserved specific PATs for endogenous palmitoylation of estrogen, progesterone, and androgen receptors, their membrane trafficking and signal transduction, as was shown in cancer cells." (PMID 34769186, 2021).
infection (1 paper, 2024). The state of being infected such as from the introduction of a foreign agent such as serum, vaccine, antigenic substance or organism. "After 16 h infection, Zdhhc7−/− BMDMs still maintained a weak signal of pIRF3, while in WT BMDMs, pIRF3 was back to resting state due to the clearance of the virus." (PMID 39141356, 2024). "The activation of IRF3 was dependent on IAV-multiplicity of infection (MOI), and Zdhhc7−/− BMDMs had weaker response in both low and high MOI conditions." (PMID 39141356, 2024).
ZDHHC7 also shares sentences with these, for which no sentence is quoted: Arthritis (1 paper); colorectal cancer (1); depression (1); dilated cardiomyopathy (1); experimental autoimmune encephalomyelitis (1); glioma (1); Glucose intolerance (1); graft versus host disease (1); Hyperglycemia (1); immune disease (1); kidney cancer (1); nervous system disease (1); osteosarcoma (1); pancreatic cancer (1); prostate (1); prostate adenocarcinoma (1); prostate carcinoma (1); Sepsis (1); systemic lupus erythematosus (1); testicular germ cell tumor (1); type I diabetes (1).